CD4 (CD4 molecule)
Diseases named in the same sentence as CD4 in open-access papers (continued):
Sharing a sentence is not in itself a finding about the gene and the disease.
tumor (continued). "Most animals of the combined αPD-1/α4-1BB ICI group demonstrated a stable or increased tumor core/margin ratio at the later imaging time point, suggesting that α4-1BB therapy increased the influx of CD4+ T cells into the TME." (PMID 40561008, 2025). "The exploratory study indicated a higher infiltration of CD4+/CD8+ CXCR5+ T follicle helper cells, CD8+CD103+ tissue-resident memory T cells, and B cells in tumor tissue, associated with better response and prognosis." (PMID 40404633, 2025). "To identify metabolic constraints within the cancer and T cell compartments in response to immune checkpoint blockade therapy, we administered anti-PD1 (αPD1) to CD4-Cre:RiboTag tumor-bearing mice and conducted DualRP analysis." (PMID 40389477, 2025). "CD4+ T cells represent another crucial component of anti-tumor immunity due to their ability to regulate immune responses, warranting significant attention." (PMID 40611261, 2025). "We found a significant increase in the number of CD45+ cells per gram of tumor following mDKN01 administration, with CD4+ and CD8+ T cells, F4/80+ macrophages, and NK cells being the most increased subsets." (PMID 39885132, 2025). "In patients with serous ovarian cancer, the severity of PNI is negatively correlated with the infiltration of CD4+ T cells in tumor tissue." (PMID 40421086, 2025). "Specifically, we assessed the dynamics of tumor infiltration by immune cells, focusing on adaptive immunity markers CD4, CD8, and GrB." (PMID 40007542, 2025). "Depletion of these cells strongly impaired the effect of the ENO1‐DNA vaccine in limiting tumour growth and improving survival in IL17A‐deficient mice, while in IL17A+/+ mice, the role of CD4+ T cells was much more crucial." (PMID 40831074, 2025). "A recent study has highlighted that CD4+ T cells and the intratumoral immune triad are necessary for the cytotoxicity and tumor elimination of CD8+ T cells at the effector-stage." (PMID 40277945, 2025). "While antitumor effects of the CD40L-CD40 axis in dendritic cell activation by CD4+ T cells have been documented, its ability to remodel the tumor microenvironment has previously been studied." (PMID 40397730, 2025). "Increased infiltration of CD3+ and CD4+ immune cells into the tumor microenvironment was observed, suggesting an enhanced immune response and potential therapeutic benefits, including reduced tumor growth." (PMID 40236954, 2025). "Recruited by CD4+ T cells, M1 macrophages acquire the ability to eliminate pre-malignant senescent hepatocytes 20, thereby preventing tumor initiation." (PMID 40860134, 2025). "In-vitro treatment of probiotics in PBMCs shows increased CD8+ T cell/Treg cell ratios, higher IFN-γ production by NK, CD4+ T, and γδ T cells, improved tumor recognition, and enhanced cytotoxicity and tumor growth inhibition via differentiation." (PMID 41471890, 2025). "This indicates that TLS with GC response represents a “functional” subtype, and the development of GC indicates the initiation of tumor-specific B cells and CD4+ T cells." (PMID 40612858, 2025). "B7-H3 antibody labeled 131I decreased the proliferation of GB cells and induced transformation of tumor phenotype from “cold” to “hot” by increasing number of CD4+ and CD8+ infiltrating tumors and inducing polarization of M2 macrophages to M1 in mouse models." (PMID 40801642, 2025). "Traditionally, CD4+ TILs were believed to function in immune regulation during tumor resistance primarily." (PMID 40444078, 2025). "LAP+CD4+ Foxp3+ T cells are a subgroup of Tregs and are enriched in blood and tumor tissues of patients with colorectal cancer." (PMID 40053558, 2025).
tumor (continued). "In patients with MSI-H CRC, mRNA-4157 was found to be safe, well tolerated, and capable of inducing neoantigen-specific CD8+ and CD4+ T cell responses, leading to both partial and complete tumor responses." (PMID 40733666, 2025). "Collectively, Sora promotes the differentiation but not the proliferation of Treg cells, leading to the expansion of tumor-infiltrating immunosuppressive Treg cells by modulating the VEGFR/ Akt/Foxo1 pathway in CD4+ T cells, thus conferring Sora resistance." (PMID 39743020, 2025). "Recent studies on tumor‐infiltrating T cells have also shown that cytotoxic CD4+ T cells play a critical role in tumor surveillance, with the ability to kill tumor cells in a class II MHC‐dependent manner." (PMID 41235706, 2025). "As a result, the number of Tregs in tumor tissues were reduced and the conversion of CD4+ T cells to Tregs was markedly inhibited." (PMID 40270603, 2025). "Flow cytometry revealed that MEKi combined with radiotherapy boosted tumor-infiltrating CD4+ and CD8+ T cells in vivo, enhancing their cytotoxic and secretory functions." (PMID 41368644, 2025). "Samples from selected treatment cycles were used to assess tumor burden based on the fraction of circulating CD4+CD26− malignant cells measured by flow cytometry." (PMID 40723261, 2025). "In PDAC tumor models, the knockout of Gal-4 substantially enhances infiltration of CD4 + and CD8 + T cells, alongside increased levels of activated CTLs, M1 macrophages, and antigen-presenting cells." (PMID 40134029, 2025). "Tumor-associated antigens provoke a tumor-specific immune response, leading to activation of MHC class I-restricted CD8+ T cells and MHC class II-restricted CD4+ T cells, with the latter exerting essential regulatory and effector roles in antitumor immunity." (PMID 41320679, 2025). "Among lymphocytes, CD4+ T cells are well-known for their role in anti-tumour responses either through either direct action and/or by recruitment of other immune cells." (PMID 40321251, 2025). "The combination of VZV-vax with the HPV16 L1165-173 and the tumor-specific E744-62 peptide led to an increase in IFN-γ-producing CD4+ T cells against the VZV gE protein and of L1-specific and E7-specific CD8+ T cells measured by dextramer staining." (PMID 40280970, 2025). "Alleviation of immunosuppression by CD14+ TAMs allows stronger CD4+ T cell responses to tumor antigen stimulation." (PMID 40872773, 2025). "In advanced tumors, mice treated with vvDD-IL-23 developed long-lasting systemic anti-tumor immunity, significantly increasing CD4+ and CD8+ T cells in tumors, whereas Treg cells were unaffected." (PMID 40469178, 2025). "We found abundant presence of CD4+ T cells in the tumor microenvironment, which have been reported to produce cytotoxic interferon gamma and induce senescence of tumor cells." (PMID 40613043, 2025). "The survival of RS cells within the tumor microenvironment exhibits greater dependence on the PD-1/PD-L1 axis or EBV infection signaling than on CD4+ T-cell abundance." (PMID 40969752, 2025). "These macrophages inhibit CD8+ and CD4+T cell proliferation in vitro and enhance tumor growth by PD-L1 in vivo." (PMID 40297580, 2025). "As expected, CXCR5 + CD4 + Tfh cells were localized in TLSs and also present in the tumor center and invasive margin, with increased numbers in early CRC." (PMID 40287532, 2025). "The anti-tumor effect of IL-10 depends on CD8+ or CD4+ T cell activity, contrary to some who have suggested that the anti-tumor action of IL-10 is caused by increased NK cell activity." (PMID 40933989, 2025). "A recent study revealed that interactions between intratumoral CD4+ T cells and B cells induce the generation of tumor-specific follicular helper T (Tfh) cells; these Tfh cells then secrete IL-21 to enhance the anti-tumor effects of CD8+ T cells." (PMID 41285707, 2025).
tumor (continued). "To better understand how the MO-I-1151 inhibitor enhanced the anti-tumor effect of DNA vaccination, we performed in vivo depletion of CD4+, CD8+, or NK1.1+ cells using monoclonal antibodies." (PMID 40655119, 2025). "High numbers of tumor-associated CD8+ and CD4+ T cells, with Th1 profile, and of PB- and tumor-associated NK cells have been correlated with better prognosis in CRC." (PMID 40607422, 2025). "In parallel, patients’ data were analyzed and showed that TXNIP is highly expressed in T lymphocytes and that its expression is reduced in tumor-infiltrating CD4+ T cells compared to those in paired normal adjacent tissue and blood." (PMID 40260243, 2025). "Studies have shown that CD4 T cells, especially CD4 memory T cells, are critical for immunotherapy-induced tumor regression." (PMID 40960294, 2025). "Our findings demonstrated a significant increase in the proportion of CD8+ T cells upon B7-H3 KO, while the proportion of tumor-infiltrating CD4+ T cells remained relatively unchanged between the groups." (PMID 39990209, 2025). "Mechanistically, apCAFs have been shown to enhance the activation and killing ability of CD4+ T cells, as well as promote M1-like macrophage polarization, thereby creating a positive feedback loop that boosts anti-tumor immunity." (PMID 40940809, 2025). "The activation of dendritic cells is boosted by the conjugation of tumor antigens with gold nanoparticles, resulting in more robust priming of CD4+ T cells." (PMID 40860882, 2025). "Meanwhile, CD4+ T cells, which primarily play supportive and regulatory roles, were significantly downregulated, partly due to tumour‐mediated suppression." (PMID 41200753, 2025). "Targeting TIM-1 to inhibit B cells can amplify anti-tumor CD8+ and CD4+ T-cell responses and suppress tumor growth." (PMID 40356928, 2025). "Controlled and forced expression of CIITA in MHC class II-negative hepatocellular cell lines rendered them MHC class II-positive and allowed for better recognition of tumor antigens by CD4+ helper T cells." (PMID 40141198, 2025). "In particular, assessment of long-term immune memory and the phenotypic and functional properties of CD8+ and CD4+ T cells after treatment will be critical to understanding the potential for durable anti-tumor immunity." (PMID 40943370, 2025). "RT-qPCR analyses of tumor tissues and splenic CD4+ T cells revealed an upward trend in IL-2 expression, prompting further investigation into IL-2 expression within the lymphatic system." (PMID 40343532, 2025). "ScRNA-seq analysis of ccRCC has demonstrated that Tregs are more abundant within tumor tissues and metastatic tissues, whereas CD4 + T cells are more prevalent in normal tissues." (PMID 41035074, 2025). "CD8+ T cells primarily activate anti‐tumor immunity, whereas CD4+ T cells are more likely to contribute to sustained immune responses and long‐term survival." (PMID 41394962, 2025). "Pyrrolidine-based CD4 stood out due to its enhanced stability, higher tumor retention, and minimal off-target effects, while partial renal elimination was observed through bladder clearance." (PMID 41304872, 2025). "At the same time, CD4+ T cells can regulate the tumor microenvironment by secreting cytokines like IL-12 and IL-21, further promoting CD8+ T cell infiltration and function." (PMID 40936903, 2025). "The results revealed that immune cells known to play critical roles in anti-tumor immunity, including CD4+ T cells, CD8+ T cells, B cells, myeloid cells, and NK cells, were more abundant in the HC1LC2 group." (PMID 40808964, 2025). "High IL-7 levels inhibit STAT5 phosphorylation and nuclear translocation, reducing CD4+T cell proliferation and impairing their anti-tumor immune function, thereby promoting PDAC development." (PMID 39958351, 2025). "Analysis of the cancer-immunity cycle revealed a positive correlation between SPOP and T cell recruitment and activation, particularly in CD8+ and CD4+ T cells, which are essential for anti-tumor immunity." (PMID 40657370, 2025).
tumor (continued). "Our study revealed a significant increase in activated memory CD4+ T cells and plasma cells within the tumor microenvironment of NSCLC patients." (PMID 41155558, 2025). "Among the key players in tumour immunology, Traditionally, CD4+ T-cells have been acknowledged for their role as helper cells that support cytotoxic CD8+ T-cell responses and B-cell activation." (PMID 40860882, 2025). "Tumor‐associated macrophages (TAMs), myeloid‐derived suppressor cells (MDSCs), and CD4+ regulatory T cells are immunosuppressive and promote tumor progression." (PMID 40384989, 2025). "By presenting antigens to both CD8+ cytotoxic T cells and CD4+ helper T cells, DCs contribute to anti-tumor activity." (PMID 40508074, 2025). "The combination of CMA-R848 and cisplatin significantly reduced tumor burden and enhanced CD4+ and CD8+ T cell populations, suggesting a shift from a “cold” to a “hot” tumor microenvironment." (PMID 41228373, 2025). "Their tumor microenvironment shows richer infiltration of immune cells, with significant enrichment of dendritic cells, CD4+ T cells, and B cells." (PMID 40872487, 2025). "Probiotic treatments increase anti-angiogenic cytokines, particularly IFN-γ and TNF-α in PBMCs, NK cells, and T cells (CD8+, CD4+, and γδ T cells); these cytokines can inhibit tumor growth by promoting differentiation." (PMID 41471890, 2025). "These immune cells, including B cells, CD8+ T cells, CD4+ T cells, macrophages, neutrophils, and dendritic cells, are essential in the anti-tumor immune response." (PMID 40612864, 2025). "In both studies, discrimination of cytotoxic CD4+ T cells with tumor cytolytic activity was enabled by flow cytometric sorting of CD4 protein–expressing cells, to distinguish them from conventional CD8+ T cells." (PMID 40299576, 2025). "CD4+ Th1 cells further bolster anti-tumor immunity by secreting pro-inflammatory cytokines (e.g., IFN-γ) and promoting the activation and functionality of CD8+ T cells." (PMID 40539049, 2025). "IHC experiments were conducted on the tumor tissue to assess the infiltration of CD4 + and CD8 + CAR T cells across different treatment groups." (PMID 40764989, 2025). "Previous studies have found that DCs, macrophages, CD4+ T cells, and dendritic cells are important immune cells in the body, playing a wide range of anti-tumor effects 39,40." (PMID 39991584, 2025). "The intrinsic sensitivity of tumor cells to IFN-γ-induced apoptosis is a major determinant of CD4+ CAR-T cell therapy." (PMID 39981247, 2025). "CD4+ T cells in this new scRNA-seq sub-atlas originated from tumor, adjacent normal tissue and blood samples." (PMID 40260243, 2025). "Use of HDAC inhibitor along with PD1 blockade, significantly improved the proliferation of tumor infiltrating CD4+ and CD8+ T-cells." (PMID 40236693, 2025). "With regard to the CD4+ T cell subsets, only CD4+ cluster 4 showed a significantly increased distance from tumor cells in PWH compared with PWOH (P = 0.05)." (PMID 40459946, 2025). "The results of flow experiments showed that A. fumigatus treatment did not significantly alter the proportions of macrophages, dendritic cells, Treg cells and CD4+ T cells in the tumor microenvironment (Fig. EV3A–D)." (PMID 41249582, 2025). "In tumor tissue rich in the DGAT1 gene displayed raised survival was related with CD4 + T cells and dendritic cell." (PMID 40554491, 2025). "In a pancreatic cancer animal model, the deletion of α-SMA + CAFs led to an increase in CD4 + Foxp3 + regulatory T cells within the tumours, resulting in accelerated tumour growth." (PMID 39780187, 2025). "Depletion of both T cell subsets led to pronounced tumor growth, providing evidence that tumor-infiltrating CD4+ and CD8+ T cells both have a critical role in driving antitumor immune responses of Notch-driven SCLC tumors." (PMID 40627448, 2025). "It has been shown that resting CD4 memory cells exhibit diminished anti-tumor immunity relative to activated CD4 memory T cells." (PMID 40510161, 2025).
tumor (continued). "The upregulation of activation markers such as 4-1BB on CD8+ T cells and OX40 on CD4+ T cells upon autologous tumor stimulation provides functional evidence of tumor reactivity." (PMID 40806287, 2025). "In a recent study targeting SCLC, apCAFs were shown to promote glycolysis in tumor cells and induce the formation of Tregs from naive CD4+ T cells in an antigen-specific manner." (PMID 40244052, 2025). "TNBC and HER2+ murine models treated with peptide-pulsed DCs demonstrated increased levels of IFN-gamma secretion and antigen-specific anti-tumor CD4+ Th1 cells within the TDLN and splenocytes." (PMID 40333343, 2025). "Generally, CD8 + T-cells are understood to be crucial in tumour immunity, while CD4 + T-cells are known to enhance tumour invasion." (PMID 39616233, 2025). "As in most cancers, natural killer (NK) cells are depressed in CLL, and the normal high ratio of CD8+ to CD4+ T cells is inverted with a consequent decreased immune tumour surveillance and cytotoxicity." (PMID 40347057, 2025). "Collectively, these data suggest that DB treatment enhances infiltration of anti-tumor Th1 (CD4+) and CD8+ cytotoxic T cells, while decreasing infiltration of Treg cells, into tumors." (PMID 40867314, 2025). "The upregulated MHCII on residual tumor cells facilitates programmed polyfunctional CD4+ T cells for tumor control and for recall responses." (PMID 39885128, 2025). "Lidocaine suppressed IL-10 secretion in CD14+ tumor-infiltrating macrophages and CD4+CD25+ tumor-infiltrating Tregs." (PMID 40244064, 2025). "There is evidence that GBM can eradicate Th1-related cytotoxicity and CD4+ T-cells from tumor tissues." (PMID 40727443, 2025). "Molecular studies demonstrated that the short-term HS diet induced the inflammatory activation of naïve CD4+ T cells to the Th17/Th1 anti-tumor phenotype." (PMID 40563574, 2025). "CD4+ T cells play a crucial role in antitumor immunity by modulating tumor cell lysis and the tumor microenvironment." (PMID 40104395, 2025). "The vaccine PRGN-2009 targets the viral oncogenic proteins E6 and E7, significantly increasing the number of CD8+ and CD4+ T cells within the tumor microenvironment." (PMID 40539072, 2025). "The expression of B7-H4 and PD-L1 in CD8+ T cells and CD4+ T cells was significantly increased in the circulation and tumor tissue of BC patients." (PMID 40489835, 2025). "Recent studies have also demonstrated that adding specific signal peptides to mRNA sequences encoding tumor antigens can promote presentation via MHC class II molecules, thereby stimulating CD4+ T helper cell responses." (PMID 40733666, 2025). "Reports have showcased clear tumor inhibition following pFUS in 4T1 tumors, where exposures were reported to increase CD4+ T cells, CD8+ T cells, DCs, and NK cells within tumors." (PMID 39971377, 2025). "At the tumor periphery, high-grade ccRCCs showed significantly higher percentages of CD4 + and CD8 + cells than low-grade ones." (PMID 39751643, 2025). "Adoptive cellular therapies containing TH1 neo-antigen-specific CD4+ T cells have also been shown to induce tumour regression in several case reports and a Phase I/II trial." (PMID 40801654, 2025). "CD4 T cells can target tumor cells in a number of ways, either by direct elimination of tumor cells through cytolytic mechanisms or by indirect regulation of TME." (PMID 40367233, 2025). "In line with ethical considerations, we used a pulmonary B16-OVA tumor model, which requires fewer CD4+ cells (and therefore fewer mice for cell production) than subcutaneous tumor models do to achieve a therapeutic effect." (PMID 40195474, 2025). "These neighborhoods included tumor-rich, CD4-rich, CD8-rich, and TAM-rich neighborhoods corresponding to similar RCNs as those in our study." (PMID 40772779, 2025).